ALB (albumin)
Diseases named in the same sentence as ALB in open-access papers (continued):
Sharing a sentence is not in itself a finding about the gene and the disease.
tumor (continued). "Since transient binding with albumin enables longer retention in blood for various compounds, it is also conceivable that a radioligand-albumin complex transiently reaches a higher concentration in the PSMA-negative tumor than in the blood itself due to the EPR effect." (PMID 34439163, 2021). "Furthermore, the serum albumin is capable of accumulating at tumor tissues or sites of inflammation." (PMID 34869202, 2021). "Albumin is widely used in oncology as a single molecule and nanoparticle carrier, as it accumulates in tumor lesions and inflamed tissues through the enhanced permeability and retention (EPR) effect, and possesses multiple cellular receptors and ligand binding sites." (PMID 33920126, 2021). "Albumin levels in urine, a marker for renal glomerular damage, were measured after eight days, one and a half, respectively, six months post-injection in non-tumor bearing animals and after three- and 28-days post-injection in mice with LNCaP tumors." (PMID 33579037, 2021). "Therefore, the in situ albumin-bound Al-ProD greatly enhances tumor accumulation with prolonged in vivo half-life and induces a potent antitumor efficacy by selectively releasing free DOX in cathepsin B-overexpressed tumor cells." (PMID 35056979, 2021). "Conjugates of MTX with albumin showed a beneficial effect on the inhibition of tumour growth." (PMID 32643014, 2021). "The primary strategy for the delivery of albumin-encapsulated liposomes is based on the concept that liposomes with a size of ~200 nm can passively accumulate into the tumor and the inflammatory site, a process that is referred to as the enhanced permeability retention (EPR) effect." (PMID 33810483, 2021). "The included inflammation indexes (such as the NLR, MLR, PLR, SII, and SIRI) and AFP, which were derived from peripheral blood counts (e.g., neutrophil, lymphocyte, and platelet) and acute-phase proteins [e.g., C-reactive protein (CRP) and albumin], represented enabling tumor characteristics." (PMID 34869272, 2021). "(radius, exophytic/endophytic properties, nearness of tumor to collecting system or sinus, anterior/posterior) nephrometry score, lymphocyte to monocyte ratio (LMR), prognostic nutrition index (PNI) and albumin to globulin ratio (AGR) were significantly associated with pT3a upstaging." (PMID 34136403, 2021). "Similarly, markers of inflammation, such as CRP, albumin or leucocyte-based ratios, were shown to predict tumor progression in a variety of solid tumors." (PMID 34148164, 2021). "Hence, the serum albumin level is indicative of tumor progression in the context of cancer-related inflammation." (PMID 33789590, 2021). "In this context, some tumor cell-related properties may hinder the efficiency of these albumin-vanadium conjugates and should be considered in preclinical and clinical settings." (PMID 34683850, 2021). "The results clearly demonstrated that the albumin theranostic can significantly suppress the tumor." (PMID 33451058, 2021). "Gender, age, BMI, tumor diameter, stage, differentiation, surgical methods, chemotherapy, lymphocyte count, albumin, CA19-9, hemoglobin, platelet, aspartate transaminase, alanine transaminase, pre-albumin, and CRP in the training group were included in LASSO regression." (PMID 34136406, 2021). "A recent study used neutrophils loaded with Abraxane (nanoparticle albumin bound paclitaxel) to serve as a Trojan horse; when they reach the radiated tumor site, the Abraxane could be released into tumor via NETosis and exert tumor killing function." (PMID 34868992, 2021). "The univariate analyses of factors associated with post-RFA fever indicate that the male sex, serum albumin level, general anesthesia, tumor diameter, tumor number, and overlapping ablation were associated with post-RFA with statistical significance (p < 0.05)." (PMID 34771466, 2021).
tumor (continued). "Active brain metastases, a higher number of metastatic sites, lower albumin and absolute lymphocyte count (ALC), higher C-reactive protein (CRP) and neutrophil-to-lymphocyte ratio, higher total metabolic tumor volume (TMTV), and higher ctDNA levels were associated with worse survival." (PMID 33418936, 2021). "Chansu injection is now being widely administered to inhibit bacteria, fight viruses, suppress pain, reduce inflammation, inhibit the proliferation of tumor cells, increase the patient's albumin level after radiochemical therapy, and induce tumor cell apoptosis." (PMID 34671410, 2021). "Notably, the PBTC group had better tumor differentiation, less intraoperative blood loss, and higher values for lymph node ratio (LNR), albumin, carcino-embryonic antigen (CEA) and cancer antigen 125 (CA125) compared with the PHC group." (PMID 33968745, 2021). "Albumin is the most abundant protein in the blood and has 17 disulphide bonds with one free thiol from unpaired cysteine (Cys34), which has emerged as a versatile protein carrier to improve the PK profile of anticancer drugs for tumor targeting." (PMID 35056979, 2021). "The endpoint was the total survival period, and the evaluation markers included the lymphocyte count and albumin level in peripheral blood obtained 4 weeks preoperatively, age, sex, alcohol consumption, smoking history, site of the tumor, pathological stage, and surgery status." (PMID 33482792, 2021). "We report on the synthesis of fluorophore-labeled homocystamide conjugates of human serum albumin and their use in thiol-‘click’ chemistry to prepare novel multimodal boronated albumin-based theranostic agents, which could be accumulated in tumor cells." (PMID 34770947, 2021). "Fourth, AFP, albumin, and initial tumor size independently predicted HCC TGR." (PMID 34966854, 2021). "Zhou prepared albumin-based perfluorotributylamine NPs (PFTBA@Alb) that could selectively inhibit tumor platelets and enhance vascular permeability." (PMID 34930293, 2021). "Most research suggests that preferential tumor uptake is mediated by organic anion-transporting polypeptides (OATPs), but recent evidence also suggests a clear role for albumin and the use of endocytosis mechanisms in the uptake and persistence of these tumor-specific dyes." (PMID 34141613, 2021). "In addition, low serum albumin level is also a marker of the systemic inflammatory response, which can promote tumor proliferation, invasion, and migration." (PMID 34234871, 2021). "According to the results of univariate Cox regression analysis, there were nine variables related to RFS: WHO histologic types, T stage, Tumor capsule status, Invasion of great vessels, ALB, Neutrophils (NE), NLR, PLR and systemic immune-inflammation Index (SII)." (PMID 34294070, 2021). "The nanoparticle albumin-bound paclitaxel could disrupt the tumor stromal structure and increase delivery of gemcitabine in PDAC patients." (PMID 34066839, 2021). "Tumor height and albumin were included in the final prediction model." (PMID 34765541, 2021). "In this retrospective study, we aimed to determine the prognostic value of MTV and TLG in PTLD patients, together with other variables of interest, such as the International Prognostic Index (IPI), organ transplant type, EBV tumor status, time after transplant, albumin levels and PTLD morphology." (PMID 33738643, 2021). "To evaluate such potentials, we first tested the permeability of the endothelial lining in the vascularized hypoxic tumor model with 70 kDa fluorescent Dextran, which mimics the size of serum albumin (66 kDa) and is often retained in the healthy vasculature within 60 min of infusion." (PMID 34571851, 2021).
tumor (continued). "However, the high albumin group had a significantly better ASA score, tumor grade, hemoglobin concentrations, and serum albumin levels than the low albumin group, whereas the low albumin group had more patients with a high CKD stage (P = .001)." (PMID 34232194, 2021). "The association between PNI and nutritional and immune statuses might reflect tumour progression and aggressiveness through the lymphocyte count and albumin level." (PMID 34130648, 2021). "We suggest that lower albumin levels may act as a biomarker for an anti-inflammatory immune environment in PAs, which is suggestive of invasive tumor behavior." (PMID 34765541, 2021). "Of note, the tumor tissue was found to feature significantly less albumin transcripts, which might reflect dedifferentiation." (PMID 34360569, 2021). "Cox analysis also revealed three independent prognostic predictors for OS: serum albumin ≥4.0 g/dL (hazard ratio, 0.29; 95% CI, 0.10–0.85; P = 0.025), tumor size ≥ 3.5 cm (hazard ratio, 3.59; 95% CI, 1.12–11.58; P = 0.032), and G8 score maintenance (hazard ratio, 0.08; 95% CI, 0.03–0.22; P < 0.001)." (PMID 33671388, 2021). "Furthermore, albumin reduces oxidative stress in tumor microenvironments via its anti-oxidant properties." (PMID 34895201, 2021). "Demographics and tumor characteristics according to Serum Albumin Level." (PMID 34123859, 2021). "Albumin delivers platinum agents efficiently to tumor tissue via these complexes." (PMID 34895201, 2021). "There is biological plausibility for the link between low AGR and increased cancer incidence and mortality: an increase in cytokines in the tumor microenvironment may elevate the total protein levels, with induced albumin synthesis suppression in the liver." (PMID 34128338, 2021). "Therefore, the ability of a drug to interact with albumin would likely result in enhanced tumor tissue retention and reduced clearance." (PMID 34141613, 2021). "Our data first verified that atovaquone effectively alleviated tumor hypoxia by inhibiting mitochondrial activity both in vitro and in vivo, and successfully encapsulated atovaquone in vesicle with albumin, forming HSA-ATO NPs of approximately 164 nm in diameter." (PMID 34600560, 2021). "Similarly, the study using an S-nitrosated human serum albumin dimer was recently published, showing the synergistic effect when used as a pretreatment agent in albumin-bound paclitaxel nanoparticle (Abraxane®) therapy carried on various tumor models." (PMID 33578756, 2021). "However, these systems exhibit little interaction with serum proteins (e.g., human serum albumin), which presumably impacts their pharmacokinetic profile and tumor exposure." (PMID 34163845, 2021). "We have identified three parameters by their hazard ratios in a multiple Cox proportional hazard model on death and used them as a three-parameter group combination (PVT, tumor multifocality, and serum albumin levels) to compare the differing patterns of clinical characteristics and survival." (PMID 33546234, 2021). "In the original data, differences in distributions were characterized in several variables, including sex (SD = 0.302), ALT (SD = 0.727), albumin (SD = 0.184), tumour size (SD = 0.469), tumour differentiation (SD = 0.194), BCLC (SD = 0.424), GGT (SD = 1.648) and ALBI grade (SD = 0.251)." (PMID 34583704, 2021). "Chronic activation of the IL-6/JAK/STAT pathway in the tumor and its microenvironment produces a deregulated inflammatory cascade at cellular and systemic levels (increased C-reactive protein, neutrophil counts and decreased albumin)." (PMID 32145060, 2020). "In pancreatic KRAS-mutated cancer cells, which can proliferate using albumin as the extracellular source of leucine, loss of SLC38A9 or its transport function strongly inhibited mTORC1 activation by macropinocytosed albumin as evidenced by cell proliferation and tumor formation." (PMID 33511116, 2020).
tumor (continued). "It has been hypothesized that the accumulation of albumin in the tumor interstitium is facilitated by SPARC." (PMID 31858848, 2020). "As such, we believe that the albumin nanoparticles presented in this paper with desirable characteristics including the induction of strong anti-tumor response, precise control, and superior safety profiles hold strong potential for preclinical and clinical anticancer therapy." (PMID 32906686, 2020). "We found higher pericyte coverage of tumor blood vessels and less albumin extravasation." (PMID 32668709, 2020). "Hybrid gold–albumin nanoparticles showed higher tumor targetability and photothermal activity." (PMID 32806755, 2020). "Preclinical mouse models have showed that combined administration of a fusion protein, consisting of a Fc domain and integrin targeting peptide, with albumin/IL-2 or anti-PD-1 immunotherapy was able to significantly enhance anti-tumor immunity and improve survival." (PMID 32752094, 2020). "Under the same conditions, Pt NPs outperformed albumin-bound Paclitaxol in tumor targeting." (PMID 31992692, 2020). "Therefore, it is meaningful to assemble ICG and albumin in a rational way to construct an optimized nanoplatform for augmenting the effects of tumor diagnosis and image-guided cancer therapy." (PMID 32183838, 2020). "Thus, PIC-loaded albumin NPs show strong inhibition of migration of the tumor cells in both CaCo-2 and HT29 cells, but free PIC has less efficiency against migration." (PMID 31906321, 2020). "Additionally, the results of our Cox regression analysis showed that many tumor behavior parameters, including tumor number, tumor diameter, TNM staging and liver function parameters such as ALB, are statistically significantly associated with TTR or OS." (PMID 32025379, 2020). "Serum albumin has protective effects such as nutrition and anti-inflammatory, and fibrinogen can promote tumor cell invasion and metastasis through epithelial-mesenchymal transition and induce tumor blood vessel formation, thereby participating in tumor progression." (PMID 33299415, 2020). "In summary, our large dataset of elderly HNSCC patients shows the prognostic strength of the blood parameters hemoglobin, GFR, CRP and albumin, representing established features of the tumor and normal tissue biology such as oxygenation, kidney function, inflammation and nutritional status." (PMID 32604773, 2020). "It was reported that albumin uptake was enhanced in tumor tissues." (PMID 32290201, 2020). "The binding of albumin to gp60 induces gp60 clustering and association with caveolin-1 (Cav-1), leading to the formation of caveolae that will carry the albumin complexes from the apical to the basal membrane, where the caveolae content is released into the tumor interstitium." (PMID 31858848, 2020). "The univariate Cox regression models revealed that mortality was associated with LNM, tumor stage, satellite nodules, single/multiple tumors, PVTT, vascular infiltration, IATO, presence of ascites, tumor size, and values for PT, neutrophil count, albumin, TBIL, TC, AST, and γ-GTT." (PMID 32568098, 2020). "Herein, a tumor microenvironment (TME)-responsive intelligent bimetallic nanoagents (HSA-Pd-Fe-Ce6 NAs) composed of human serum albumin (HSA), palladium-iron (Pd-Fe) bimetallic particles, and chlorin e6 (Ce6) was designed for effective combination phototherapy." (PMID 32457891, 2020). "In addition to the gastric outlet status, the significant prognostic factors of survival included age; the tumor size; the prealbumin, albumin, and Hb levels; the Borrmann type; pT; pN; and curability." (PMID 32774358, 2020). "However, the highest changes of blood biochemical parameters were observed in 4T1 tumor-bearing mice from the 100 IU+cal group, which had decreased phosphate and albumin levels and increased total protein in the plasma." (PMID 33172201, 2020).
tumor (continued). "Thus, delivering chemotherapeutic drugs loaded in albumin nanoparticle functions as a Trojan horse for killing tumor cells and the FDA approved AbraxaneTM is an outcome of this concept." (PMID 32438691, 2020). "Due to the natural abundance of albumin in the blood, nanomedicines with albumin surface modification may have lower immunogenicity and can be preferentially absorbed by the tumor cells." (PMID 33437580, 2020). "Albumin, in particular, as either a drug conjugate or nanocarrier, can improve circulation time of the drug, facilitate increased tumor tissue accumulation via the enhanced permeability and retention (EPR) effect, and overcome drug resistance." (PMID 33134314, 2020). "The measured distributions in tumor are much smaller than the co-infused albumin." (PMID 32967184, 2020). "In this study, we developed a hypothesis‐generating risk scoring system based on four variables to represent systemic inflammation (PLR), tumor microenvironment (liver metastasis), nutritional status (albumin), and clinical presentation (ECOG PS)." (PMID 32100417, 2020). "SPARC is known to facilitate albumin accumulation in tumor stroma." (PMID 33114661, 2020). "Receiver operating characteristic (ROC) curves, using 5-year OS rates as the end-point, for the SII, the PNI, the NLR, leukocyte count, neutrophil count, fibrinogen level, hemoglobin level, prealbumin level, albumin level, globulin level, and tumor size were generated." (PMID 32596318, 2020). "DMSO modifies the metabolic activity of Huh-7 tumor cells to give a phenotype similar to that of primary hepatocytes by increasing the secretion of albumin or alpha-1 antitrypsin; this stimulates the replication of strain JFH-1 of the Hepatitis C virus (HCV) in vitro." (PMID 31991673, 2020). "Similarly, three tumour samples that clustered close to adjacent liver samples showed high levels of Albumin mRNA (10.69, 6.87, and 4.25%) compared to the mean Albumin expression in the tumour samples (0.65% ± 1.87)." (PMID 32195184, 2020). "Similarly, treatment with bovine serum albumin coupled with gold nanorods showed strong immune-stimulatory responses of DCs and tumor suppression." (PMID 33298099, 2020). "However, the stage, tumor location, serum albumin, surgical approach, neoadjuvant chemotherapy history, and rectal resection proportion were significantly different between the groups." (PMID 32046725, 2020). "DOX-MAC, as used in our study, had the albumin nanoparticle as a drug carrier to effectively extravasate into the tumor region under the ultrasound exposure and to release doxorubicin in the acidic environment around the tumor." (PMID 33306731, 2020). "Compared with patients with tumor size no more than 5 cm, the mutation percentages of ALB, FBN3, HSPG2, and FLG2 were increased in patients with tumor size more than 5 cm." (PMID 32017470, 2020). "By 3 h, however, the albumin-bound [68Ga]ABY-028 had spread throughout most of the tumor." (PMID 32960353, 2020). "Serum albumin level may be a surrogate of poor nutritional and inflammatory status as well as an aggressive tumor behavior." (PMID 33585232, 2020). "Our findings revealed a strong relationship between serum GDF-15 concentrations and the disease spectrum (ranging from SMM to ISS stage III MM), as well as correlations between circulating GDF-15 and indices of tumor burden (albumin, β2-microglobulin), which fall in line with earlier reports (; J.)." (PMID 33144847, 2020). "Other patient characteristics such as age, sex, ethnicity, performance status, tumor type, initial tumor burden, serum albumin level, initial lactate dehydrogenase level, liver function, and renal function have not been shown to affect PK parameters in a clinically relevant manner." (PMID 32714874, 2020).